MTOR (mechanistic target of rapamycin kinase)
Diseases named in the same sentence as MTOR in open-access papers (continued):
Sharing a sentence is not in itself a finding about the gene and the disease.
tumor (continued). "In our study, the lapatinib + palbociclib combination treatment, targeting the HER2/AKT/mTOR signaling pathway and inhibiting the CDK4/6-Rb bypass pathway, significantly inhibited the survival of tumor cells and induced apoptosis." (PMID 37160904, 2023). "Evidence demonstrated that following intravenous administration of gedatolisib, it inhibits both mTOR and PI3K kinases, inducing apoptosis and suppressing the growth of tumor cells overexpressing PI3K/mTOR." (PMID 37046703, 2023). "Corroborating the in vitro findings, the tumours from the DPC‐treated mice exhibited reduced pERK as well as lower expression of HES1 and mTOR." (PMID 37165578, 2023). "LncRNAs have been reported to affect autosis in tumor cells by regulating the ULK1 complex and mTOR signaling pathway." (PMID 37313458, 2023). "Our results show that metformin inhibits HER2+ GC cell proliferation and tumor growth, possibly by suppressing HER2 phosphorylation and inhibiting the mTOR pathway." (PMID 37835462, 2023). "GOLPH3 promotes tumor cell proliferation, survival, migration and invasion via various mechanisms including activating the PI3K/Akt/mTOR signaling pathway as well as altering Golgi morphology and vesicular trafficking." (PMID 37508488, 2023). "The PI3K/AKT/mTOR activity, under the regulation of PIK3AP1, regulates T-cell homeostasis, as well as tumor survival and metabolic adaptation." (PMID 38223508, 2023). "In line with this, the inactivation of the Abelson (ABL) murine leukaemia viral oncogene homolog (ABL1), upregulated in HLRCC tumours by inhibition of the protein-tyrosine phosphatase N12 PTPN12, led to the suppression of mTOR-mediated HIF1α translation." (PMID 37689804, 2023). "We previously demonstrated that miR-494 contributes to sorafenib resistance via mTOR pathway activation in HCC cells and showed that miR-494 inhibition enhances the anti-tumor effect of sorafenib in rats." (PMID 37301960, 2023). "A Sleeping Beauty forward genetic screen using 119 primary tumours and 134 metastatic nodules also revealed enrichment in the PI3K/AKT/mTOR and MAPK pathways." (PMID 36681687, 2023). "Western blotting revealed that apatinib significantly promotes mTOR phosphorylation in mouse tumor tissues, while FMD treatment leads to a significant inhibition of mTOR phosphorylation and HIF-1α expression." (PMID 37884960, 2023). "Likewise, a fully controlled response may be associated, for instance, with the counteraction of tumor-induced cachexia and the inhibition of catabolic pathways (IL-6, TNF-alpha) balanced with the stimulation of anabolic pathways (FoxO3a, p-AKT, p-mTOR, and P-GSK-3β)." (PMID 37895979, 2023). "This tumor resistance was explained by the ability of IL-6 to induce the phosphorylation of tumor AKT, mTOR and NF-κB signaling." (PMID 37190141, 2023). "Simultaneously, the S100A8/A9–SSSRs axis participates in many aspects of tumor initiation and development, usually involving MAPKs, NF-κB, PI3K/Akt, and mTOR along with the assistance of VEGF, YAP, Nrf2, and HIF-1." (PMID 37701037, 2023). "mTOR inhibition decreased the proliferation of ESCC cell lines and showed similar results in an in vivo model, which further sensitized the tumor to cisplatin resistance." (PMID 37444412, 2023). "We showed that pharmacological inhibition of the PDGFR and PI3K/mTOR pathways with imatinib mesylate and PKI-587 effectively suppressed tumour growth in vivo." (PMID 36522480, 2023). "A neutral polysaccharide known as LBP‐1 has exhibited remarkable anti‐tumor activity by inhibiting the growth of A549 tumor cells, blocking the cellular G0/G1 phase, and regulating the PI3K/Akt/mTOR signaling pathway to induce apoptosis." (PMID 38107149, 2023).
tumor (continued). "The anti-tumor efficacy of the “winning” combination of EGFR (erlotinib) and MTOR (MLN0128) inhibitors was further mechanistically investigated in culture and in vivo." (PMID 36831214, 2023). "Liu and colleagues indicated that phosphorylation and expression of mTOR and AKT were reduced in HBXIP‐inhibited tumour cells." (PMID 37156724, 2023). "The PTEN gene inhibits tumor growth by negatively regulating PI3K and its downstream targets (mTOR/AKT, etc.)." (PMID 36647780, 2023). "While mTOR is one of the most common downstream effectors, the main critical regulator of the PI3K/AKT pathway is the phosphatase and tensin homologue (PTEN) tumour suppressor." (PMID 36765661, 2023). "Several cell signaling pathways, such as Akt/mTOR and MAPK, are involved in the processes of growth, survival, migration, and invasion of tumor cells." (PMID 37190229, 2023). "Here, we validated the two tumor suppressor genes, STK11 and NF2, involved in the mTOR signaling pathway which have been suggested as promising oncogenic therapeutic targets in recent studies." (PMID 37351538, 2023). "KLF5 enhances the phosphorylation of the mammalian target of the rapamycin (mTOR) via the activation of PI3K/AKT signaling, thereby inhibiting autophagy in melanoma cells and enhancing tumor cell survival." (PMID 36761967, 2023). "A decrease in tumor sphere formation and CaP progression was observed in CaP cells when EpCAM was targeted, with a significant decrease in PI3K/AKT/mTOR expression, suggesting that EpCAM can be the therapeutic target to inhibit CaP progression." (PMID 37895357, 2023). "Contrastingly, mTOR activity in T cells is inhibited by glucose competition when PD-L1 and B7-H3 expression is found in tumor cells, where it promotes aerobic glycolysis by activating the PI3K-Akt-mTOR pathway." (PMID 36677919, 2023). "This major signaling pathway promotes adaptive tumor processes and helps in the activation of other hypoxia-induced pathways, including PI3K/Akt/mTOR, NOX, Wnt/β-Catenin, and Hedgehog signaling pathways promoting tumor survival." (PMID 36787054, 2023). "One of the most common tumor-related signaling pathways, the PI3K/AKT/mTOR signaling pathway, exhibits aberrant hyperactivation in a range of tumor forms, including breast cancer, colorectal cancer, and RCC, making it a key target for cancer therapy." (PMID 37176098, 2023). "Although this network is complex, it is a master regulator of tumour development and progression, therefore, there have been extensive efforts to develop targeted therapies against PI3K/AKT/mTOR signalling." (PMID 37857607, 2023). "As evidenced by the results of western blotting of tumor tissue samples, DA markedly abrogated activation of c-Met, PI3K, Akt, mTOR, MEK, and ERK." (PMID 37835375, 2023). "The combination of monensin and rapamycin in tumor tissues significantly decreased p-PI3K, p-AKT, and p-mTOR expressions compared to the control group." (PMID 37370314, 2023). "Temsirolimus is the other small molecule inhibitors of mTOR, and part of the PI3K/AKT pathway involved in tumor cell proliferation and angiogenesis approved by FDA for advanced RCC." (PMID 37169756, 2023). "Cachexia group showed low phosphorylation level of mTOR, p70s6k, and 4E-BP1, especially the mice bearing IDH1-mutant tumor." (PMID 37741882, 2023). "In their study, berberine reduced the tumor size to 60% via activation of AMPK and reduction of mTOR activities." (PMID 37560308, 2023). "The data show that EIF4G1 promotes tumor cell proliferation and the G1/S transition of cell cycle in LSCC, then the biological function of LSCC is effected by the AKT/mTOR pathway." (PMID 36897548, 2023). "The PI3K/AKT/mTOR and ERK1/2 MAPK pathways are crucial for modulating the malignant phenotypes of tumor cells, including cell survival and apoptosis." (PMID 37953768, 2023).
tumor (continued). "However, targeting a single kinase component within PI3K/AKT/mTOR signaling pathway typically results in tumor growth arrest as opposed to apoptosis, which may be caused by abnormal activation of other compensatory pathways." (PMID 37955668, 2023). "It has been revealed that overexpression of these transporters reduced the efficacy of dual PI3K/AKT/mTOR inhibitors, such as LY3023414, in tumor cells." (PMID 37046703, 2023). "Lymphocyte infiltration and the expressions of different proteins on tumor cells (CD56, CD15, CD68, and ph-mTOR) were analyzed." (PMID 37190322, 2023). "The mTOR-inhibitor rapamycin prevents the expression of the SASP induced by radiation treatment and thereby inhibits tumor progression." (PMID 36980745, 2023). "More importantly, we showed that IFI35 was secreted by tumor cells and promoted the proliferation and cytotoxicity of CD8+ T cells by activating the PI3K/AKT/mTOR signaling pathways." (PMID 37380972, 2023). "Researchers report that C21 steroidal glycosides can inhibit tumor cells by regulating the Wnt/β-catenin signaling pathway, TLR4/MyD88/NF-κB, AKT signaling pathway, PI3K/AKT/mTOR signaling pathway, and Hippo pathway." (PMID 36985801, 2023). "Since the expression of HIF-1α is regulated by mammalian target of rapamycin (mTOR), the amount of 18F-FDG in tumor cells also depends on mTOR signaling." (PMID 36536190, 2022). "PTEN, which is a tumor suppressor, regulates the PI3K/AKT/mTOR pathway involved in cell survival and proliferation." (PMID 36010952, 2022). "We separately assessed some common functional pathways by ssGSEA algorithm, including: PI3K/Akt/mTOR pathway, cellular hypoxia response, EMT-related genes, G2M checkpoint, angiogenesis, tumor proliferation, and so on." (PMID 36078096, 2022). "Treg growth is induced by reduced mTOR signaling via FOXO3 expression; Tregs with the forkhead box 3+ (FOXO3+) gene play a crucial role in tumor immunity by suppressing effector T cells." (PMID 36428613, 2022). "Anti‐tumor activity of PI3K and mTOR inhibitors has been shown in human PTCL cell lines and mouse models with constitutive PI3K/AKT pathway activation." (PMID 35510955, 2022). "Sorafenib can inhibit the invasion and proliferation of tumor cells via the RAS/MEK/ERK and PI3K/Akt/mTOR pathways." (PMID 36380016, 2022). "The phosphorylation curve shows that the mTOR pathway is activated by the disrupted function of the TSC1/2 complex, which proves that the carcinogenic lineage of PEComa is a unique TSC2-related tumor." (PMID 35928867, 2022). "Activity in terms of reduction of tumor volumes was noted to be significantly enhanced in patients with molecular alterations in the drug targets (RET, VEGFR, EGFR, and PI3K/mTOR), supporting further development of the combination." (PMID 34551970, 2022). "The combined inhibition of PI3K/Akt/mTOR and the Shh dual pathways and knockout or inhibition of HIF-1α can help reduce the migration ability of tumor cells and prolong the postoperative survival of patients." (PMID 35935338, 2022). "An IMPAGT analysis revealed immune dysregulation even at the tumor budding stage, especially in the PI3K/Akt/mTOR axis, with a high efficiency and integrity." (PMID 36354662, 2022). "After one week of tumor growth, we started to treat the mice by oral administration with AKT and mTOR inhibitors—i.e., MK-2206 and RAD001." (PMID 35454789, 2022). "The Western blotting results showed that PPII lowered phospho-AKT, phospho-mTOR, phospho-STAT3, phospho-Src, and Bcl-XL and upregulated the LC3B-II protein level in tumor tissues." (PMID 36233191, 2022). "Some recent studies have shown that inflammatory interferon regulates cellular metastasis, vasculogenic mimicry, and antiapoptosis activity of tumor cells, mainly activating the PI3K/AKT/mTOR pathway." (PMID 35342418, 2022). "Therefore, the mTOR signaling pathway could effectively target through anti-tumor therapy studies." (PMID 36251702, 2022).
tumor (continued). "HIF-1α is essential for lactate-mediated activation of GPR81/mTOR/HIF-1α/STAT3 pathway, and inhibition of lactate production in tumor cells or HIF-1α expression in MDSC can restore the immune response of antitumor T cells." (PMID 36686771, 2022). "Recently, several studies indicated that zotatifin inhibited tumor cell proliferation and induced cell apoptosis by modulating phosphatidylinositol 3-kinase/protein kinase B/mammalian target of rapamycin (PI3K/AKT/mTOR) pathway." (PMID 36182930, 2022). "For example, DEFB1, the human antimicrobial peptide defensin β 1, is considered as a potential tumor suppressor gene and has been shown to mediate PI3K/mTOR signaling, thereby leading to death of tumor cells." (PMID 35938006, 2022). "Quercetin inhibited the PI3K/Akt/mTOR and STAT3 pathways in PEL cells, reducing the survival of the tumor cells and leading to cell death." (PMID 36291856, 2022). "Consistent with suppression of tumour glycolysis, activation of phosphatidylinositol-3-kinase (PI3K), AKT and mammalian target of rapamycin (mTOR) in CRC tumours was also markedly inhibited by cold exposure." (PMID 35922508, 2022). "The beneficial anti-tumor outcome is induced through AMPK signaling, which suppresses mTOR activity." (PMID 35454306, 2022). "We noted enrichment of oncogene and tumor suppressor pathways in the Ptenfl/fl mice, including upregulation of AKT and mTOR, which are expected in this model." (PMID 36511483, 2022). "ER and PR target several oncogenes that are known to impact tumor cell metabolism including MYC and PI3K/AKT/mTOR that increase glucose transport, glycolysis, and lipid synthesis." (PMID 35406548, 2022). "AMPK and TNF receptor signaling (e.g., MTOR, MAP4K1) were overrepresented in the tumor tissues of EDAC at the protein and phosphoprotein levels." (PMID 35397555, 2022). "The mTOR-dependent regulation of STAT3 and NF-κB activity promoted an immunosuppressive microglial phenotype, thereby contributing to tumor immune evasion and invasive growth in vivo." (PMID 35920986, 2022). "Blocking the CCL5/CCR5 axis induced decreased endothelial cell migration, which was related to decreased activity of the mTOR /Akt pathway, while CCL5 promoted tumor angiogenesis through the PKC δ/c-Src/HIF-1 α/VEGF signaling pathway." (PMID 35784750, 2022). "Here, we assessed the expression of mTOR, PI3K, and Akt1 on our tumor tissue sections following our treatment regimens." (PMID 35892853, 2022). "TET promoted autophagy of tumor cells and induced cell death, which was related to the inhibition of PKC-a and the inactivation of mTOR." (PMID 35109761, 2022). "ITZ itself can inhibit mTOR and VEGF2 simultaneously by inhibiting the operation of cholesterol, while VEGF siRNA can directly silence the highly expressed VEGF gene in tumor cells." (PMID 35890264, 2022). "Our subsequent analysis provided potential chemotherapy regimens for this type of tumor, including MDM2, MEK, and mTOR inhibitors." (PMID 36569894, 2022). "In this study, we employ multi-omics approaches based on bulk and single-cell transcriptomic datasets to investigate the role of MAP2K1, mTOR, YAP1 and EGFR in the tumor immune context of tumor microenvironment." (PMID 35655775, 2022). "We hope this review will promote a comprehensive understanding of the role of the PI3K/AKT/mTOR and RAF/MEK/ERK signaling pathways in facilitating tumors and will help direct drug selection for tumor therapy." (PMID 36539659, 2022). "Subsequently, the synergistic antitumor effect of co-treatment with RFA, si-PD-1, and si-TGF-β was confirmed in a xenograft model by measuring the tumor growth, survival rate, infiltration of CD8+ T cells, and activity of the PI3K/AKT/mTOR pathway." (PMID 35354382, 2022). "Metformin can inhibit tumor in many ways, including regulating the PI3K (phosphatidylinositol 3-kinase), mammalian target of rapamycin (mTOR), AMP-activated protein kinase, and MAPK (mitogen-activated protein kinase) signaling pathways." (PMID 36033393, 2022).
tumor (continued). "For this research work, the drug delivery nanoplatform HPDA-ABS/PEG-BEZ235/Ce6 (H-APBC) in combination with phototherapy has been constructed to increase intracellular acidity, inhibit PI3K/mTOR signal and attenuate HIF-1α-dependent tumor hypoxia adaptation." (PMID 35413842, 2022). "Tumor-specific research should be a severe issue, and appropriate dosing regimens need to be explored to make PI3K/AKT/mTOR inhibitors more tolerable and efficient." (PMID 35402264, 2022). "Metformin reduces the risk of CRC, reducing serum inflammatory factors, and inhibits tumor growth through the AMPK/mTOR pathway, mTOR/AKT pathway, and LKB1/AMPK pathway, thus facilitating the prognosis of patients." (PMID 36505896, 2022). "We found that knockdown of Peg3 significantly attenuated mTOR hyperactive HCC tumorigenesis and metastasis using subcutaneous xenograft mouse model and tail-vein intravenous injection in vivo, indicated by tumor volume, tumor weight, and lung metastasis." (PMID 36451866, 2022). "Among the downstream kinases MEK plays therapeutically an important role, besides, mTOR, BRAF, AKT, as MEK is frequently up regulated in tumor cells." (PMID 35814409, 2022). "We determined that three oncogenes, PD-L2, ETV5, and MTOR and 113 long intergenic non-coding RNAs (lincRNAs) were constantly up-regulated, whereas two oncogenes, BCR and GTF2I, one tumor suppression gene MEN1, and 30 lincRNAs were constantly down-regulated." (PMID 35317849, 2022). "The proportions of tumor-infiltrating immune cells (TIICs) in the TME varied significantly between low and high MTOR expression groups." (PMID 35883111, 2022). "Instead of directly targeting VEGF, an indirect approach was recommended for materializing dual-modulation of the tumor vascular system and TME through VEGF/HIF-1 mediated by the PI3K/Akt/mTOR cascade and preventing drug resistance." (PMID 35784750, 2022). "Together, we found a novel tumor-suppressing role of GLUD1 in ccRCC which was different from that in other tumors and a new mechanism for inhibiting PI3K/Akt/mTOR activation and TIME in ccRCC." (PMID 36203437, 2022). "In conclusion, knockout of MUC3A inhibited tumor proliferation, invasion, and chemoresistance in CRC via the PI3k/Akt/mTOR signaling pathway." (PMID 35655161, 2022). "Concomitant targeting of PI3K/mTOR with either HER2 or mGluR1 inhibitors results in decreased cell survival and tumor growth in xenograft studies." (PMID 35086953, 2022). "PTEN is a tumor-suppressor gene regulating cell cycle, proliferation, and apoptosis via different pathways including the AKT/mTOR, which upregulates PD-L1 expression in PC." (PMID 35203446, 2022). "In an analysis of 19,784 tumor samples from 60 countries, aberrations in the PI3K/AKT/mTOR pathway were identified in 38% of solid tumors overall, with the highest frequency seen in endometrial cancer." (PMID 36039910, 2022). "QR regulates many signalling pathways, for instance the AMPK, mTOR, and PI3K-AKT pathways and can affect the growth of tumor cells and induce apoptosis." (PMID 36605099, 2022). "We have previously shown tumour hypermutation, dysregulation of PI3K/MTOR signalling and high neoantigen load correlate with response to therapy." (PMID 35860583, 2022). "We have shown that the crucial process of extravasation coincides with PAM pathway activation in the tumor cell, and can be successfully reduced by dual PI3K/mTOR inhibition." (PMID 34216217, 2022). "Under hypoxia and in the tumor microenvironment, the PI3K/Akt/mTOR signaling pathway is activated, inhibiting autophagy." (PMID 35163356, 2022). "Data from our in vitro, in silico, and in vivo experiments showed that HF exerts antitumor effects against ESCC by inhibiting tumor growth and promoting apoptosis through the PI3K/AKT/mTOR signaling pathway." (PMID 35178352, 2022). "Recent studies suggest the IGF/PI3K/mTOR pathway and YAP/TAZ paralogs regulate cell fate and proliferation in response to biomechanical cues within the tumor microenvironment." (PMID 35284040, 2022).